PRKCA (protein kinase C alpha)
Diseases named in the same sentence as PRKCA in open-access papers (continued):
Sharing a sentence is not in itself a finding about the gene and the disease.
esophagitis (2 papers, 2017 to 2018). An acute or chronic inflammatory disease affecting the esophageal wall. "Interestingly, we found that PLCE1 and PRKCA mRNA levels were even more elevated in severe esophagitis, compared to mild/moderate esophagitis." (PMID 28402280, 2017). "Based on the model of esophagitis initiation and progression, we hypothesized that PRKCA might form a partnership and close correlation with PLCE1 along with the whole process of esophageal inflammation initiation, progression and tumorigenesis." (PMID 28402280, 2017).
intestinal cancer (2 papers, 2013 to 2019). "Studies in mice showed that a PRKCA knockout led to the spontaneous formation of intestinal cancer." (PMID 31795319, 2019).
lymphoma (2 papers, 2014 to 2022). A malignant (clonal) proliferation of B- lymphocytes or T- lymphocytes which involves the lymph nodes, bone marrow and/or extranodal sites. "In other cell models, such as lymphoma cells, alpha-tocopherol was shown to downregulate V-Myc Avian Myelocytomatosis Viral Oncogene Homolog (MYC), lactate dehydrogenase (LDH) and protein kinase C-alpha (PRKCA) gene expression." (PMID 24587218, 2014).
oral cancer (2 papers, 2015 to 2022). "Therefore, it is reasonable to conclude that PRKCA plays important roles in the development of oral cancer." (PMID 26064958, 2015).
peripheral nerve injury (2 papers, 2020 to 2023). Injury to a peripheral nerve. "Following peripheral nerve injury, impaired neurons release this molecule into the synaptic environment, acting on IGF1R on DRG neurons and consequently mediating an enhancement of protein kinase C alpha (PKCα)-dependent T-type calcium currents to increase pain." (PMID 37266437, 2023).
renal carcinoma (2 papers, 2017 to 2023). A carcinoma arising from the epithelium of the renal parenchyma or the renal pelvis. "The significant increase of PLCE1 and PRKCA was also observed in renal cancer and Yolk Sac Seminoma." (PMID 28402280, 2017).
rhabdomyosarcoma (2 papers, 2021 to 2024). A rare aggressive malignant mesenchymal neoplasm arising from skeletal muscle. "Genetic knockdown of PRKCA significantly protected rhabdomyosarcoma (RMS) cells from erastin-induced cell death." (PMID 34475496, 2021).
tongue cancer (2 papers, 2021 to 2026). A malignant neoplasm affecting the tongue. "Our results suggest that PRKCA levels may serve as a molecular marker of an emerging high-risk subgroup of young tongue cancer patients." (PMID 33923093, 2021).
acute lung injury (1 paper, 2022). A condition of lung damage that is characterized by bilateral pulmonary infiltrates (pulmonary edema) rich in neutrophils, and in the absence of clinical heart failure. "EGCG pre-treatment alleviates LPS-induced acute lung injury (ALI) in mice through the inhibitory effect of protein kinase C alpha (PRKCA) on pro-inflammatory cytokine release through mitogen-activated protein kinase (MAPK) signaling pathways." (PMID 36139757, 2022).
alcohol dependence (1 paper, 2021). Physical and psychological dependence on alcohol. "PRKCA has been associated with alcohol dependence and early onset of alcohol dependence for European Americans and African Americans in the GWAS." (PMID 33540941, 2021). "Four SNPs in PRKCA (rs17688881, rs721429, rs7217618, and rs8077110) are associated with alcohol dependence and brain activations." (PMID 33540941, 2021).
atopic eczema (1 paper, 2020). A common chronic pruritic inflammatory skin disease with a strong genetic component. "Anti-allergenic effect of atopic eczema can be achieved through the inhibition of CD44 and protein kinase C alpha (PKCα) interaction by HA." (PMID 32848737, 2020).
bacterial vaginosis (1 paper, 2016). Infection caused by bacterial overgrowth in the vagina. "Polymorphism in genes for Protein kinase C alpha (PRKCα) and IL6 interact with bacterial vaginosis and confer increased risk for PTB." (PMID 27766960, 2016).
benign fibrous histiocytoma (1 paper, 2024). A benign neoplasm composed of fibroblastic spindle cells in a whorled storiform pattern. "In a gene fusion study in benign fibrous histiocytomas, KIRREL was found to be chimeric with PRKCA thus confirming the involvement of KIRREL and PRKCA in the development of benign fibrous histiocytomas." (PMID 37909722, 2024).
brain cancer (1 paper, 2025). A primary or metastatic malignant neoplasm affecting the brain. "The penetrant D463H mutation in PRKCA, which encodes the kinase PKCα, is a biomarker and driver of chordoid glioma, a type of brain cancer." (PMID 41187221, 2025).
Burkitt lymphoma (1 paper, 2012). A rare form of malignant mature B-cell non-Hodgkin lymphoma. "We find for instance exonic deletions in the potential oncogene PIGU, and intronic deletions in PRKCA, which is overexpressed in some Burkitt's lymphomas." (PMID 23171647, 2012).
cervical squamous cell carcinoma (1 paper, 2017). A squamous cell carcinoma arising from the cervical epithelium. "PRKCA was significantly increased from 1.09 ± 0.22 in normal cervix (n = 10) to 1.35 ± 0.47 in cervical high grade introepithelial neoplasm (HGN, n = 7) and 1.37 ± 0.08 in cervical squamous cell carcinoma (n = 21)." (PMID 28402280, 2017).
developmental delay (1 paper, 2023). "In our experiments, we also found abnormal PRKCA gene expression in raccoons with developmental delay, which suggests that the PRKCA gene has a regulatory role in the health of both humans and animals." (PMID 37762538, 2023).
diabetic retinopathy (1 paper, 2025). "Berberine also appears to be a promising preventive or adjuvant treatment for diabetic retinopathy, and its key protective effect may involve the regulation of RGCs apoptosis through the GABA-alpha receptor/protein kinase C-alpha (GABAAR/PKC-α) pathway." (PMID 40943905, 2025).
fibromyalgia (1 paper, 2021). A chronic disorder of unknown etiology characterized by pain, stiffness, and tenderness in the muscles of neck, shoulders, back, hips, arms, and legs. "Previous studies revealed that differentially methylated PRKCA was both involved in development of fibromyalgia and RHD, which were usually caused by inflammatory cytokines and suffered from rheumatic symptoms." (PMID 34482802, 2021).
gout (1 paper, 2021). A condition characterized by painful swelling of the joints, which is caused by deposition of urate crystals. "Therefore, the key mechanism of M. alba L. leaves against gout might be to suppress the inflammasomes in synovial fluids by inhibiting AKT1 by γ-Tocopherol, PRKCA by 4-Dehydroxy-N-(4,5-methylenedioxy-2-nitrobenzylidene) tyramine, and PLA2G2A by Lanosterol acetate on the RAS signaling pathway." (PMID 34502281, 2021).
laminopathies (1 paper, 2020). "Protein kinase C alpha (PKC-α) interacts with lamin A/C and with several lamin A/C partners involved in striated muscle laminopathies." (PMID 33142761, 2020).
lung injury (1 paper, 2023). "In addition, PRKCA has been shown to have a significant inhibitory anti-inflammatory effect on some diseases, such as acute lung injury." (PMID 37287061, 2023). "Besides, PRKCA has been shown to have significant anti-inflammatory effects on some diseases, such as acute lung injury." (PMID 37287061, 2023).
Mitral stenosis (1 paper, 2021). An abnormal narrowing of the orifice of the mitral valve. "In the present study, mitral valve tissues from three mitral stenosis patients with RHD by valve replacement and two healthy donors were harvested and conducted DNA methylation signature on PRKCA by MeDIP-qPCR." (PMID 34482802, 2021).
myocardial ischemia (1 paper, 2022). A disorder of cardiac function caused by insufficient blood flow to the muscle tissue of the heart. "In our study, the expression level of heart PRKCA was enhanced, while PRKCE was reduced upon myocardial ischemia, and their levels returned to normal following the pretreatment of XML injection." (PMID 35141226, 2022). "Based on the results of network pharmacology analysis, first, the top four genes (PRKCA/MAPK3/PRKCG/PLA2G4A) and PRKCE (an isoform of the large PKC family) were picked up for validation in the animal model of surgery-induced myocardial ischemia." (PMID 35141226, 2022).
nephrolithiasis (1 paper, 2021). The presence of a calculus in the pelvis of the kidney; this is most often composed of mineral salts and proteins. "Genes in this crosstalk include those previously reported to be of functional relevance to nephrolithiasis, such as protein kinase C (PRKCA, PRKCB, and PRKCZ), markers (CD40 and TLR3), and autophagy (MTOR and SQSTM1), thus validating our genetic prioritization at the gene and pathway level." (PMID 34489936, 2021).
omphalocele (1 paper, 2018). Omphalocele is an embryopathy classified in the group of abdominal celosomias and is characterized by a large hernia of the abdominal wall, centered on the umbilical cord, in which the protruding viscera are protected by a sac. "In our study, downregulation of WNT11, PRKCA and CaMK2D genes after TiO2 NPs treatment (10 μg/ml) possibly interfered with actin-cytoskeleton organization, cell movement and cell adhesion, thus disrupting noncanonical Wnt/Ca2+ signaling that resulted in omphalocele." (PMID 29555972, 2018).
Onset (1 paper, 2022). The age group in which disease manifestations appear. "PKCα is one of the three highly penetrant variants in the PRKCA gene, identified by whole-genome sequencing of 1345 individuals from 410 families with late-onset AD." (PMID 36172481, 2022).
opioid use disorder (1 paper, 2024). A substance-related disorder that involves the recurring use of opioids despite negative consequences. "We identified three genes linked to impulsivity—SLCO5A1, PRKCA, and PRKCH—in infants born to mothers with opioid use disorders." (PMID 39238930, 2024).
pancreatic adenocarcinoma (1 paper, 2020). "Finally, protein kinase C-alpha (PKCα) phosphorylates the Thr1172 residue within the L1CAM cytoplasmic domain, thus regulating important properties of pancreatic adenocarcinoma cells such as motility." (PMID 32429448, 2020).
pneumococcal pneumonia (1 paper, 2021). A febrile disease caused by STREPTOCOCCUS PNEUMONIAE. "In patients with pneumococcal pneumonia, PRKCA has a role in the activation antibiotic-induced release of pneumolysin." (PMID 34409086, 2021).
polycystic ovary syndrome (1 paper, 2025). A disorder that manifests as multiple cysts on the ovaries. "Additionally, research has demonstrated that asparagus can effectively increase oestrogen receptor α levels in ovariectomised rats and alleviate polycystic ovary syndrome symptoms through its antioxidant and anti-inflammatory effects via the PRKCA pathway." (PMID 39837933, 2025).
psychosomatic disorders (1 paper, 2025). "This review first outlines how epigenetic dysregulation contributes to psychosomatic disorders through altered expression of genes such as GRM2, TRPA1, SLC6A4, NR3C1, leptin, BDNF, NAT15, HDAC4, PRKCA, RTN1, PRKG1, and HDAC7." (PMID 41439979, 2025).
rheumatoid arthritis (1 paper, 2006). A chronic, systemic autoimmune disorder characterized by inflammation in the synovial membranes and articular surfaces. "Barton and co-workers observed both linkage to the region and association to a marker D17S807, which is located next to the PRKCA gene, in rheumatoid arthritis ASP families, when studying human loci syntenic to two rat models of inflammatory arthritis." (PMID 16596167, 2006).
severe acute respiratory syndrome (1 paper, 2021). A viral respiratory infection caused by the SARS coronavirus. "Similar to MSI2, PRKCA has also been linked to severe acute respiratory syndrome (SARS) in humans, which is caused by a SARS-CoV-1." (PMID 34409086, 2021).
type 1 diabetic nephropathy (1 paper, 2005). "PECAM-1 is located near protein kinase C alpha, an enzyme implicated in albuminuria during type 1 diabetic nephropathy." (PMID 16371158, 2005).
cancer (200 papers, 2007 to 2025). A tumor composed of atypical neoplastic, often pleomorphic cells that invade other tissues. "Then, risk scores were calculated for every cancer sample calculated by using the following formula: Riskraw = DAD1*2.316+CYCS*1.426+CSNK2A2*1.576+VPS25*0.728+VDAC1*0.976+TMLHE*0.381+CYTH3*0.024+PRKCA*0.260-TP73*0.567+FZD6*0.047+SQSTM1*0.094-MAP2K7*3.070." (PMID 35185897, 2022). "PRKCA has been associated with emotional memory formation, posttraumatic stress syndrome, cancer, and aging." (PMID 34482802, 2021). "Recent in vitro (DLD-1 cells incubated with PKCα activators) and in vivo (C57BL/6J mice) studies with knocked-out PRKCA (gene encoding mouse PKCα) confirmed that this kinase exerts an anti-tumor (anti-growth, stimulating cell death) effect on cancer cells." (PMID 33276489, 2020). "Only 95 tumors with confirmed somatic nonsynonymous mutations of PRKCA are present amongst the 30,367 tumors with available sequencing data for PRKCA in the version 81 release of the Catalogue of Somatic Mutations in Cancer (COSMIC) database." (PMID 29476136, 2018). "PRKCA encodes the Protein kinase C (PKC) isozyme alpha (PKCα) and is mutated in a wide range of human cancers." (PMID 29915258, 2018). "Together, these results identify PRKCA as a novel, recurrently mutated oncogene in human cancer." (PMID 29476136, 2018). "Other KDs were associated with signal transduction and kinase activity (PRKCA, TAOK1, and ADRBK1), membrane transport (SLC9A3R1), metabolism (PPP1R3B), gene regulation (USF1), and immune responses and cancer (SLAMF8, SRC, and KIAA0100)." (PMID 41402937, 2025). "Accumulated evidence shows that Protein kinase C alpha (PKCα) contributes to tumorigenesis and therapy resistance in cancer." (PMID 39596225, 2024). "The serine-threonine kinase PRKCA has been observed to be upregulated in BC, inversely correlated with ER expression and is a critical member of signaling networks in cancer stem cells, and thus is being explored as a therapeutic target in TNBC62." (PMID 39478117, 2024). "We were able to replicate the survival curve for PRKCA (P‐value = 7.5e‐3) on a separate cohort of cancer patients from TCGA using RPPA phosphorylation measures." (PMID 36688815, 2023). "Prior research has shown that the initiation of PRKCA prompts subsequent tumor-promoting consequences in various forms of cancer." (PMID 37895143, 2023). "“Pathways in cancer” and PRKCA displayed the highest indegree and outdegree distribution of 17 and 16 respectively." (PMID 38081857, 2023). "Several SNPs in different PKC isoforms (rs454006, rs2242245, and rs8103851 of PRKCG, rs11079651 in PRKCA, and rs34367566 in PRKCB) have been reported to be linked with various types of cancer." (PMID 36672978, 2023). "Protein kinase C (PKC), including PRKCB and PRKCA, is involved in diverse cellular signalling pathways, including those involved in cancer." (PMID 33241658, 2021). "Knockout studies in mice suggest that PRKCA activity regulates cancer, and PRKCA was overexpressed in PCa cells." (PMID 33540941, 2021). "NC can inhibit the expression of PRKCA by up-regulating the expression of miR-125b-2-3p and then play an anti-cancer role." (PMID 33949293, 2021). "It was discovered that not only TNF-α receptor subtypes but also transcription factors of the AP-1 family as well as protein kinase C-alpha (PKC-α) are involved in the cancer promotion-mediated inflammation, proliferation, invasion, and angiogenesis of tumors." (PMID 33917793, 2021). "Whereas PRKCA, PRKCD, or PRKCG expression levels were negatively associated with the infiltration of immune cells in some cancers and positively correlated with immune infiltration in other cancers." (PMID 35174160, 2021). "Based on our findings and the known molecular roles of PRKCA in relevant cancer pathways, we propose a model for PRKCA overexpression as a driver in the tumorigenesis of a subset of OTSCC patients." (PMID 33923093, 2021).
cancer (continued). "The upregulation of PRKCA has been observed in multiple malignant tumors and found to induce cancer cell proliferation and metastasis." (PMID 32681720, 2020). "The results showed that the expression levels of both PLCE1 and PRKCA were also elevated in above cancers." (PMID 28402280, 2017). "PRKCA has long been recognized to participate in activating tumour growth and development across different cancers." (PMID 27438146, 2016). "PKC-alpha, encoded by the PRKCA gene, is a member of the PKC family and has been implicated in cancer cell migration." (PMID 24260584, 2013). "Our results may have therapeutic implications since several compounds have been under clinical investigation to target overexpression of different PRKC isoforms, including PRKCA, in cancer patients." (PMID 33923093, 2021). "Notably, the MAPK1, AKT1 and PRKCA genes were enriched in a vast majority of vital cancer-related signaling pathways." (PMID 32665670, 2020). "CAPN2, ITPR1, PPP3CA, and PRKCA were enriched in calcium-induced T lymphocyte apoptosis pathway, and not reported on tumor-host immunological interactions, but those proteins were repeatedly reported relevant to human cancers." (PMID 31258820, 2019). "Two hypotheses suggest a role for PRKCA somatic variants in the absence of cancer in pos-neg subjects." (PMID 35589867, 2022). "Notably, we further identified multiple reported malignancy‐related genes (e.g., MET, PIK3R1, PRKCA, PTEN, SHC1, and STAT3) upregulated in HCC272, and demonstrated that these genes were mainly enriched for cancer‐related functions, which were associated with broad drug resistance." (PMID 34105295, 2021). "In addition, PRKCA activation can result in increased cell motility in several in vivo and in vitro cancer models, the effect of which may be reversed with PRKCA inhibition." (PMID 27438146, 2016). "Noteworthy, several candidate susceptibility genes (PRKCA, BMP6, ADAMTS19, ARHGAP6, FUT9/8, FAM108C1, CHL1, BTBD9 and WDR52) are involved in the actin cytoskeleton arrangement, cell adhesion and cell motility processes, which are important for cancer invasion and metastasis." (PMID 22532847, 2012). "There are 42 intersecting targets of cancer/tumor with PKVG phenolic acid-based active ingredients, and the top four DC were MAPK1, EGFR, MAPK10, and PRKCA by network analysis." (PMID 39689118, 2024). "MiR-328 deregulation has been shown to promote BM in patients with NSCLC, partially by modulation of protein kinase C alpha (PRKCA), leading to high PRKCA levels and increased cancer cell migration." (PMID 36765679, 2023). "PRKCA, a member of PKC family that plays a key role in regulating cell proliferation, survival and metastasis in cancers." (PMID 34299042, 2021). "For PRKCA, PRKCD, PRKCE, and PRKCG, the correlation between their expressions and HLAs enrichment scores were variable among different cancers." (PMID 35174160, 2021). "Otherwise, the correlations between PRKCA, PRKCD, PRKCE, and PRKCG expressions and the infiltration of the immune cells varied between cancer types." (PMID 35174160, 2021). "Subsequently, PRKCA has been shown to intersect with the MAPK/ERK and PI3K/AKT pathways, which are frequently active in several cancer types, promoting tumor progression by suppressing apoptosis and inducing proliferation, migration, invasion and angiogenesis." (PMID 33923093, 2021). "Collectively, the expression levels of PRKCI and PRKCG were elevated in most of the significantly compared cancers, while PRKCA, PRKCB, PRKCE, and PRKCQ tended to be downregulated among most cancer types." (PMID 35174160, 2021). "As such, special attention in future analyses should be paid to the linking genes PRKCA, PTPN14, POU2F1, and TGFBR1, because of their possible roles in cancer initiation." (PMID 30045691, 2018).